GPR132 (G protein-coupled receptor 132)
Diseases named in the same sentence as GPR132 in open-access papers (continued):
Sharing a sentence is not in itself a finding about the gene and the disease.
melanoma (3 papers, 2025). A malignant, usually aggressive tumor composed of atypical, neoplastic melanocytes. "The role of GPR132 in lactate is less well understood, but studies have shown that GPR132 is expressed in the human epidermis, keratinocytes, fibroblasts, melanocytes, and various skin tumors, such as malignant melanoma, compound nevus cell nevi, and basal cell carcinoma." (PMID 40046050, 2025). "Here, RNA-seq displayed that the expression of GPR132 was reduced in activated NK cells, and the proportion of mature NK cells in GPR132−/− mice was substantially increased compared to WT mice, with stronger anti-melanoma capabilities." (PMID 40043109, 2025). "Moreover, to further explore whether GPR132 deletion could promote the ability of NK cells to resist tumor metastasis, we conducted a melanoma lung metastasis experiment." (PMID 40043109, 2025). "Accordingly, we performed melanoma lung metastasis and bone marrow transplantation experiments, further demonstrating the absence of GPR132 promotes the antitumor ability of NK cells." (PMID 40043109, 2025).
neuropathic pain (3 papers, 2017 to 2025). Chronic pain caused by damage to nerve fibers. "In a mouse neuropathic pain model, GPR132 deficiency significantly reduced hypersensitivity, immune cell infiltration, and proinflammatory cytokine release, suggesting that GPR132 inhibition may offer a novel therapeutic strategy." (PMID 40340645, 2025).
colorectal cancer (2 papers, 2023 to 2025). A primary or metastatic malignant neoplasm that affects the colon or rectum. "Next, we further evaluated the ability of GPR132-knockdown CAR-NK cells to eradicate colorectal cancer in vivo." (PMID 40043109, 2025). "Compared to traditional CAR-NK cells, the GPR132-downregulated CAR-NK cells displayed enhanced cytotoxicity against colorectal cancer cells and increased the expression of GzmB and IFN-γ." (PMID 40043109, 2025). "On the basis of these findings, we down-regulated GPR132 in NKG2D/4-1BBζ-NK92 (CAR-NK92) cells to detect its anti-colorectal cancer activity." (PMID 40043109, 2025). "In the treatment of colorectal cancer xenografted mice, GPR132-downregulated CAR-NK cells exhibited excellent antitumor activity and intratumoral survival." (PMID 40043109, 2025). "The deficiency of GPR132 can attenuate the inhibition of NK cells by lactate, consequently increasing the expression of INF-γ and GzmB and effectively boosting the anti-colorectal cancer effect of CAR-NK92 cells." (PMID 40043109, 2025). "Down-regulation of GPR132 weakens the inhibition of NK cell function by lactate, thereby enhancing the functional execution of CAR-NK cells against colorectal cancer." (PMID 40043109, 2025). "In addition, the down-regulation of GPR132 in NK cells weakens the inhibition by lactate and substantially enhances the effectiveness of CAR-NK92 cells against colorectal cancer." (PMID 40043109, 2025).
Obesity (2 papers, 2023). Accumulation of substantial excess body fat. "For obesity‐induced T2DM, several class A orphan GPCRs, including GPR21, GPR35, GPR84, and GPR132, are suggested to play an active role in the developmental processes of T2DM." (PMID 36721851, 2023).
skin tumors (2 papers, 2020 to 2025). "In this study, we have examined the expression profiles of the pH-GPCRs GPR4 (GPR19), TDAG8 (GPR65), OGR1 (GPR68) and G2A (GPR132) on different types of common skin tumors, SCC, MM, NCN and BCC." (PMID 32948783, 2020).
Acidosis (1 paper, 2015). Abnormal acid accumulation or depletion of base. "Acidosis activates a family of proton sensing G-protein coupled receptors, including G-protein coupled receptor 4 (GPR4), G-protein coupled receptor 65 (GPR65), G-protein coupled receptor 68 (GPR68), and G-protein coupled receptor 132 (GPR132)." (PMID 25988385, 2015).
arteriosclerosis (1 paper, 2017). A vascular disorder characterized by thickening and hardening of the walls of the arteries. "9-HODE is the strongest ligand participating, through GPR132, in the pathogenesis of arteriosclerosis." (PMID 28655971, 2017).
coronary arteriosclerosis (1 paper, 2025). "Finally, a comprehensive analysis of blood samples from patients diagnosed with coronary arteriosclerosis was conducted to explore the lactate‐GPR132‐Src signaling pathway." (PMID 40492515, 2025).
coronary stenosis (1 paper, 2025). Narrowing of the coronary artery lumen diameter. "In clinical samples, elevated plasma lactate levels and the activation of the GPR132‐Src pathway in peripheral blood mononuclear cells (PBMCs) are positively associated with coronary stenosis." (PMID 40492515, 2025). "Clinical samples further substantiate the relationship between lactate levels, GPR132 expression, and the severity of coronary stenosis, highlighting the importance of the lactate‐GPR132‐Src pathway in mediating macrophage senescence in the context of diabetic atherosclerosis." (PMID 40492515, 2025).
endometrial carcinoma (1 paper, 2022). A malignant tumor arising from the epithelium that lines the cavity of the uterine body. "Eight IRGs were incorporated to construct a nomogram for survival prediction in endometrial carcinoma patients, including CCR7, GNA15, GPR132, LTA, MYC, NOD2, P2RX4 and P2RY2." (PMID 36207698, 2022). "Among these genes, CCR7, MYC and NOD2 have been reported in a large number of tumor studies, including endometrial cancer, while P2RX4, GNA15, and GPR132 genes have few molecular biological experiments to verify their role in endometrial cancer progress." (PMID 36207698, 2022).
gallstones (1 paper, 2024). Solid crystalline precipitates in the biliary tract, usually formed in the gallbladder, resulting in the condition of cholelithiasis. "Additionally, GPR132 has been associated with hepatic lipid metabolism and gallstone development in mice, as GPR132‐deficient mice exhibit gallstones and an increased cholesterol saturation index." (PMID 39417398, 2024).
leukemia (1 paper, 2022). A malignant (clonal) hematologic disorder, involving hematopoietic stem cells and characterized by the presence of primitive or atypical myeloid or lymphoid cells in the bone marrow and the blood. "Further investigations were warranted to define the role of GPR132 in cell cycle, cell apoptosis, and cell migration of leukemia blasts." (PMID 36437247, 2022). "We thus hypothesized that GPR132 activation by 8GL may downregulate mTOR activity by stimulating the Gαs-cAMP-PKA pathway in leukemia." (PMID 36437247, 2022). "Overexpression of GPR132 in human primary AML cells led to a significant increase in the expression level of CD11b, a surface marker for human leukemia cell differentiation." (PMID 36437247, 2022).
liver steatosis (1 paper, 2023). "To explore the underlying mechanism of 9/13-HODEs-induced liver steatosis, we investigated GPR132 expression and found deficient expression in the liver." (PMID 38071367, 2023).
lymphoma (1 paper, 2021). A malignant (clonal) proliferation of B- lymphocytes or T- lymphocytes which involves the lymph nodes, bone marrow and/or extranodal sites. "In contrast, GPR132 is highly enriched in leukemias and lymphomas and is upregulated in primary AML compared to normal hematopoietic cells." (PMID 34680233, 2021). "The small molecule compound ONC212 that specifically activates GPR132 induces apoptosis in human cell lines of myeloid and lymphoid leukemias and lymphomas, indicating a tumor suppressor function of GPR132 in hematologic malignancies." (PMID 34680233, 2021).
type 2 diabetes (1 paper, 2025). "In vivo experiments demonstrated that GPR132 deficiency significantly ameliorates metabolic disturbances induced by high-fat diet feeding, establishing a strong rationale for developing selective GPR132 modulators as potential therapies for type 2 diabetes." (PMID 40791590, 2025).
tumor (48 papers, 2013 to 2025). "The TAM surface receptor Gpr132 functions in response to lactate stimulation and induces its own M2 phenotype polarization, whereas the tumor-associated macrophage surface olfactory receptor Olfr78 has a similar effect." (PMID 40045411, 2025). "Olfr78 synergistically mediates the polarization of M2 phenotype macrophages with Gpr132, and Olfr78 functionally deficient mice exhibit the characteristics of tumor growth suppression, metastasis inhibition, and increased anti-tumor immune cell populations." (PMID 40045411, 2025). "GPR132 is a receptor expressed in tumor-associated macrophages, and the engagement of GPR132 attenuates inflammatory cytokines." (PMID 34572293, 2021). "Progression of cancer with high lactate content was significantly halted in Gpr132 knockout mice with reduced tumor-associated M2 macrophages, indicating the importance of lactate/Gpr132 axis in inducing M2 macrophages." (PMID 34359884, 2021). "An interesting example is Gpr132, located on chromosome 12, which encodes a G-protein coupled receptor with apparent tumour suppressor activity." (PMID 24586197, 2014). "Within the TME, tumor endothelial cells contribute to cancer-associated angiogenesis, while lactic acid promotes M2-like polarization via GPR132, a process regulated by the PPARγ transcription factor, which inhibits GPR132 expression." (PMID 40343509, 2025). "In addition, compared to WT mice, GPR132-deficient mice exhibited a higher survival rate, an elevated number of tumor-infiltrating NK cells, which expressed more granzyme B (GzmB) and IFN-γ." (PMID 40043109, 2025). "Lactate within the tumor microenvironment can also be sensed by GPR132 present on the cell membrane of tumor-associated macrophages, leading to induction of cAMP signaling and the downstream promotion of pro-angiogenic macrophage phenotypes and associated gene transcription program/expression." (PMID 39858494, 2025). "Mammary fat pad tumor graft experiments demonstrated that Gpr132 deletion in the DKO mice impaired the ability of macrophage PPARγ deficiency to exacerbate tumor growth because DKO mice showed similar tumor volume as Gpr132-KO mice." (PMID 27692066, 2016). "Moreover, tumor-derived lactate can induce tumor-associated macrophage (TAM) polarization to the M2 immunosuppressive phenotype by binding to the lactate-sensitive receptor-G protein-coupled receptor 132(GPR132)." (PMID 36233246, 2022). "Given the known role of LPC in modulating immune responses via the G protein–coupled receptor G2A (GPR132) and that G2A is highly expressed in macrophage and lymphocytes, we next examined immune cell populations in the tumor microenvironment using scRNA-seq." (PMID 41321310, 2025). "GPR132 mediates tumor-macrophage interactions by detecting lactate in the acidic TME, promoting the M2-like macrophage phenotype." (PMID 41366282, 2025). "In this study, the interaction between THBS2 and GPR132 was assessed in an immunosuppressive tumour microenvironment." (PMID 37884956, 2023). "Lactate interacts with GPR132 to activate downstream signalling pathways, influencing macrophage function and polarisation, particularly in inflammatory and tumour microenvironments." (PMID 37884956, 2023). "This shows the important relevance of GPR132 in peritoneal carcinomatosis tumor nodules of colorectal origin." (PMID 36902589, 2023). "The evaluation of GPR132 expression profile showed in 70% a strong expression pattern on the surface of tumor cells." (PMID 36902589, 2023). "GPR132 mediates tumor-macrophage interactions to promote the alternatively activated M2-like phenotype by detecting lactate in the acidic tumor microenvironment." (PMID 37584707, 2023). "It was found that cancer cell-derived lactate activated Gpr132 on ATMs to promote the M2 phenotype, and that lactate-Gpr132 axis-activated ATMs enhanced tumor cell metastasis, thus forming a positive feedback loop." (PMID 37564659, 2023).
tumor (continued). "In an acidic tumor environment, G protein-coupled receptor 132 (Gpr132) functions as a key macrophage sensor of the increased lactate." (PMID 37426676, 2023). "Upregulated THBS2 expression in CRC cells inhibits anti-tumour immunity through the HIF1A/lactic acid/GPR132 pathway." (PMID 37884956, 2023). "GPR132 was initially discovered to inhibit tumour development by hindering cell cycle progression and mitosis; but high levels of expression in fibroblasts caused transformation in one study." (PMID 36046070, 2020). "Lactate stimulates GPR132 on tumour macrophages, promoting the development of an M2 phenotype that enables migration and invasion of tumour cells." (PMID 36046070, 2020). "In consequence, experimental studies strongly suggest that GPR132 is relevant in cancer and point to opposite effects in different neoplasias." (PMID 33113952, 2020). "These pharmacological findings support that the PPARγ repression of Gpr132 in macrophages is a significant contributor to the anti-tumor effects of rosiglitazone." (PMID 27692066, 2016). "Our findings have opened an exciting new path for future investigations to delineate how macrophage Gpr132 senses tumor signals and then exacerbates tumor malignancy." (PMID 27692066, 2016). "Compared with WT controls, Gpr132-Het mice also showed attenuated tumor growth at a later stage, indicating that Gpr132 regulation is dosage-sensitive." (PMID 27692066, 2016). "Consequently, tumor growth is inhibited when the macrophage Gpr132 level is low by either Gpr132 deletion/inhibition or PPARγ activation via rosiglitazone; whereas tumor growth is exacerbated when the macrophage Gpr132 level is high as the result of macrophage PPARγ deficiency." (PMID 27692066, 2016). "Compared with WT and Gpr132 heterozygous (Het) controls, Gpr132-KO mice exhibited significantly diminished tumor growth." (PMID 27692066, 2016). "In vitro macrophage-tumor cell co-culture experiments showed that Gpr132-KO macrophages exhibited a significantly reduced ability to promote cancer cell colony formation and growth." (PMID 27692066, 2016). "The results showed that si-Gpr132 significantly reduced tumor volume compared with si-Ctrl, as the result of depleted Gpr132 expression." (PMID 27692066, 2016). "Consistent with this in vitro observation, the anti-tumor effect of rosiglitazone in vivo was also abolished in Gpr132-KO mice." (PMID 27692066, 2016). "Myc overexpression in tumor cells or high lactic acid levels may serve as a prognostic indicator for resistance to immune-based therapies, highlighting the Gpr132 pathway as a critical mechanistic checkpoint." (PMID 41280929, 2025). "Although Gpr132 has been identified as a pH-sensitive receptor capable of sensing lactate/acidic signals and regulating macrophage responses in tumor models, its relevance for exercise-induced angiogenesis remains speculative." (PMID 41153828, 2025). "Similarly, lactate derived from tumor cells can engage GPR132 on macrophages, promoting their polarization toward the M2 phenotype, which is associated with immunosuppression and tumor-supportive functions." (PMID 41152975, 2025). "Additionally, lactate specifically recognizes GPR132, the activation of which contributes to inflammation and tumor growth." (PMID 39169402, 2024). "Moreover, overexpressed THBS2 influenced the M2 polarisation of macrophages by interacting with GPR132, thereby affecting immune cell infiltration in the tumour microenvironment." (PMID 37884956, 2023). "Activation of GPR132 leads to an increase in lactate in the acidic tumor milieu (lactat-GPR132 axis), and activates the alternative macrophage (M2)-like phenotype, which in contrast to the “normal” macrophages facilitates cancer cell adhesion, migration, and invasion." (PMID 36902589, 2023). "Furthermore, Olfr78 forms a heterodimer with Gpr132, which promotes M2 macrophage polarization, and subsequently promotes tumor progression and metastasis." (PMID 37564659, 2023).
tumor (continued). "In fact, the tumor-secreted lactate can accelerate cell adhesion, migration, and invasion in breast cancer by facilitating the macrophage M2 phenotype, which is dependent on the activation of a GPR132-dependent manner." (PMID 36612084, 2022). "As GPR132 is identified as a novel acidic extracellular pH sensor, it can be activated following the rising lactate production from the Warburg effect and thereby, mediating some tumor effects under the acidic TME." (PMID 36612084, 2022). "Furthermore, consistent with the in vitro results, GPR132 overexpression boosted the levels of CD11b in tumor tissues." (PMID 36437247, 2022). "Furthermore, mRNA expression of GPR132, which is the key lactate sensor in tumor cells and MΦ 45, decreased in cocultured tumor cells from MCT4 KD MΦ, while MCT4 mRNA expression remained unaltered." (PMID 34158867, 2021). "Lactate-GPR132 signaling in macrophages contributes to tumor cell invasiveness and tumor growth." (PMID 34394085, 2021). "Likewise, pharmacological inhibition of GPR132 signaling had a similar effect on tumor burden and antitumor immune responses." (PMID 34394085, 2021). "Similar to GPR81, lactate signaling via GPR132 in macrophages promotes tumor growth and metastasis." (PMID 34394085, 2021). "For example, macrophage levels of PPARγ and Gpr132 may predict not only tumor aggressiveness but also the pharmacological responses to rosiglitazone or Gpr132 inhibitors." (PMID 27692066, 2016). "Functionally, macrophage Gpr132 is pro-inflammatory and pro-tumor." (PMID 27692066, 2016). "Importantly, Gpr132 deletion abolishes the cancer regulation by macrophage PPARγ or rosiglitazone, indicating that Gpr132 is an essential mediator of PPARγ functions in macrophages and tumor progression." (PMID 27692066, 2016). "Together, our in vitro and in vivo results indicate that macrophage Gpr132 promotes tumor growth, suggesting that Gpr132 inhibition may impede cancer progression." (PMID 27692066, 2016). "However, it has been shown in breast cancer cells that the activation of GPR132 in tumor-associated macrophages promotes their polarization to the non-inflammatory M2-like phenotype, thereby enhancing tumor growth." (PMID 39858494, 2025). "Similarly, PPARγ may affect many genes in macrophage, and targets other than Gpr132 may also contribute to the anti-tumor effects of PPARγ." (PMID 27692066, 2016). "For instance, lactate can bind to GPR132 on natural killer (NK) cells, suppressing the expression of interferon-γ (IFN-γ) and granzyme B (GZMB), thereby facilitating tumor progression." (PMID 41152975, 2025). "Furthermore, it has been shown that peroxisome proliferator-activated receptor γ (PPARγ) inhibits the expression of GPR132 proteins in macrophages, so targeting the lactate-PPARγ/GPR132 receptor-related pathway may have an inhibitory effect on the pro-tumor effects of TAMs." (PMID 39169402, 2024). "Tumor cell-produced lactate can promote the macrophage M2 phenotype by stabilizing hypoxia-inducible factor 1-alpha (HIF-1α) and activating g protein-coupled receptor 132 (GPR132) to induce vascular endothelial growth factor." (PMID 34722510, 2021). "The increased lactate levels in the tumor microenvironment can further induce M2 macrophage polarization by affecting HIF-1α, ERK-STAT3 signaling pathways, and G-protein-coupled receptor 132 (GPR132)." (PMID 40704062, 2025). "The results showed that overexpression of THBS2 did not significantly alter tumour volume in GPR132-KO mice." (PMID 37884956, 2023). "Tumor derived lactate also increases M2 macrophage polarization mediated by ERK-STAT3 signaling pathway, HIF-1a stabilization, and G-protein-coupled receptor 132 (GPR132) activity." (PMID 37234972, 2023).